MCTP1 (multiple C2 and transmembrane domain containing 1)
Description:
Calcium sensor which is essential for the stabilization of normal baseline neurotransmitter release and for the induction and long-term maintenance of presynaptic homeostatic plasticity.
Synonyms: FLJ22344
Tractability: Antibody: UniProt predicts a signal peptide or a membrane-spanning region. PROTAC: ubiquitination databases record sites on it; its protein half-life has been measured.
Gene: Protein-coding gene on chromosome 5 (94,703,690 to 95,285,094, reverse strand). Ensembl gene ENSG00000175471.
Subcellular location: Cytoplasmic vesicle, secretory vesicle, synaptic vesicle membrane; Recycling endosome; Endoplasmic reticulum membrane
Subcellular location (Human Protein Atlas): Golgi apparatus
Gene Ontology:
Molecular function: calcium ion binding; calcium-dependent phospholipid binding
Biological process: calcium-mediated signaling; negative regulation of cell migration; negative regulation of endocytosis; negative regulation of response to oxidative stress; regulation of neuronal synaptic plasticity; regulation of neurotransmitter secretion
Cellular component: membrane; endoplasmic reticulum membrane; recycling endosome; synaptic vesicle membrane
Genetic constraint (gnomAD): Loss-of-function variants: 40 observed, 59.39 expected, observed/expected ratio (o/e) 0.67, 90% interval 0.52 to 0.88. The upper end of that interval is the gene's LOEUF score, 0.88, which puts it in group 3 of 6, group 1 being the genes least tolerant of losing a copy. Missense variants: 876 observed, 821.43 expected, observed/expected ratio (o/e) 1.07, 90% interval 1.01 to 1.13. Synonymous variants: 405 observed, 345.49 expected, observed/expected ratio (o/e) 1.17, 90% interval 1.08 to 1.27.
Homologues: Orthologues: chimpanzee MCTP1 (99% identical), macaque MCTP1 (98% identical), pig MCTP1 (92% identical), dog MCTP1 (91% identical), rat Mctp1 (88% identical), mouse Mctp1 (87% identical), rabbit MCTP1 (74% identical), guinea pig MCTP1 (73% identical), tropical clawed frog mctp1 (66% identical), zebrafish mctp1a (54% identical), zebrafish mctp1b (52% identical), Drosophila melanogaster Mctp (34% identical), and 1 more. Paralogues in human: MCTP2 (41% identical).
Diseases named in the same sentence as MCTP1 in open-access papers:
MCTP1 is named in the same sentence as 18 diseases in open-access papers, as found by Europe PMC text mining. Sharing a sentence is not in itself a finding about the gene and the disease. The quoted sentences say what the papers report.
colorectal cancer (4 papers, 2014 to 2022). A primary or metastatic malignant neoplasm that affects the colon or rectum. "Varied expression of MCTP1 has been observed in colorectal cancer specimens." (PMID 29649113, 2018). "Differences in the expression of MCTP1 were observed in colorectal cancer specimens." (PMID 29027969, 2017). "So far, expression of MCTP1 has been investigated in only colorectal cancer with differential expression but without any clinical correlation." (PMID 29649113, 2018). "Thus far, the expression of MCTP1 was investigated only in colorectal cancer with differential expression but without any correlation to clinical data." (PMID 29027969, 2017).
bipolar disorder (3 papers, 2010 to 2021). A disorder of the brain that causes unusual shifts in mood, energy, activity levels and the ability to carry out day-to-day tasks. "Genome-wide analysis shows that MCTP1 single nucleotide polymorphism (SNP), rs17418283, is related to bipolar affective disorder." (PMID 34093644, 2021). "Interestingly, Mctp1 has previously been reported to be strongly associated with bipolar disorder in individuals of European ancestry." (PMID 19958391, 2010). "Overall, our study provides evidence for the association of CMYA5, MCTP1, RXRG, and TNR with bipolar disorder." (PMID 26190982, 2015). "We then investigate the homologous genomic regions in human bipolar disorder GWAS data and thus identify four candidate genes (TNR, RXRG, MCTP1, and CMYA5)." (PMID 26190982, 2015).
esophageal cancer (2 papers, 2021 to 2023). A primary or metastatic malignant neoplasm involving the esophagus. "Of the favorable prognosis-related genes, previous studies have reported that the downregulated MCTP1 was related to drug-resistance of esophageal cancer, and MRPS18C was the least expressed MRPS18 family member in malignantly transformed B-cells." (PMID 36816541, 2023). "All these results suggested that MCTP1 activates the drug-resistance of esophageal cancer cells, which has implications for further design of new biomarker of esophageal cancer treatment." (PMID 33571139, 2021). "As a result, the expression of MCTP1 is down-regulated in the drug-resistant esophageal cancer cells." (PMID 33571139, 2021). "The following methylation sequencing showed that the MCTP1 gene is hypermethylated in the drug-resistant esophageal cancer cells." (PMID 33571139, 2021). "Down-regulation of MCTP1 also affects the migration and apoptosis of esophageal cancer cells, as revealed by the wound-healing and apoptosis assays." (PMID 33571139, 2021). "Further investigations proposed two signaling pathways that might involve in the MCTP1-mediated drug-resistance of esophageal cancer cells." (PMID 33571139, 2021).
Anxiety (1 paper, 2015). Intense feelings of nervousness, tension, or panic often arise in response to interpersonal stresses. "We identify four genes (TNR, RXRG, MCTP1, and CMYA5) associated with anxiety in mice and risk of BD in humans." (PMID 26190982, 2015). "CMYA5, MCTP1, RXRG, and TNR are associated with mouse anxiety and human BD." (PMID 26190982, 2015). "Finally, when we correlate striatal expression of all four of our candidate genes against the large BXD phenotype dataset, we find that Tnr, Rxrg, and Mctp1 expression correlates with dopamine related traits, whereas Cmya5 expression correlates with anxiety- and depression-like traits." (PMID 26190982, 2015).
colon cancer (1 paper, 2023). "As a result of the mRNA levels in the blood from two lung cancer PDX cases and two colon cancer PDX cases, significance was found only for NCKAP1 and MCTP1." (PMID 36639705, 2023).
COVID-19 (1 paper, 2023). A disease caused by infection with severe acute respiratory syndrome coronavirus 2. "The autoantibodies identified in neuropsychiatric patients with COVID-19 and PCS are ARHGAP31, GAD65, acethylcholine receptor, D1/2, MOG, NMDAR, MCTP1, Yo, myelin, and Ma/Ta2." (PMID 37606433, 2023).
hearing loss (1 paper, 2025). "The overlap of a long-range chromatin loop between the Mctp1 and the Nr2f1 with a known hearing loss-associated deletion (dwnd_deletion) provides evidence that structural variants can disrupt enhancer-promoter interaction, leading to Nr2f1 dysregulation, even in the absence of coding mutations." (PMID 41169613, 2025).
keloid (1 paper, 2025). An irregularly shaped, elevated mark on the skin caused by deposits of excessive amounts of collagen during wound healing. "Single‐cell analysis of TGF‐β signalling indicates that immune cells are the primary signal emitters in keloids, while MCTP1+ fibs and POSTN+ mesenchymal fibs mainly act as mediators and receivers." (PMID 39902627, 2025).
mental disorder (1 paper, 2015). A disease that has its basis in the disruption of mental process. "A systems genetics approach suggests that TNR, RXRG, and MCTP1 coexpress with several other genes related to mental disorders in the striatum, providing a potential mechanism of action." (PMID 26190982, 2015). "In mice, three of our candidates (Mctp1, Rxrg, and Tnr) coexpress in the striatum with other genes related to mental disorders." (PMID 26190982, 2015). "The GeneFriends analysis suggests that MCTP1 and RXRG coexpress with mental disorder related genes." (PMID 26190982, 2015). "Finally we show that three of our four genes (Mctp1, Rxrg, and Tnr) coexpress with other genes known to be involved in mental disorders in the striatum, but not in the hippocampus, of adult BXD mice." (PMID 26190982, 2015). "However, MCTP1 and RXRG have 13 commonly coexpressed genes, which are significantly enriched for relevant disease annotations (e.g., “Brain diseases” and “Mental disorders”) and several relevant GO annotations (e.g., “Synaptic transmission”)." (PMID 26190982, 2015). "This suggests that although genes related to, for example, mental disorders are enriched in the overlap between TNR and RXRG, and in the overlap between MCTP1 and RXRG, they are not the same genes, i.e., both sets of genes are independently related to mental disorders." (PMID 26190982, 2015).
multiple system atrophy (1 paper, 2020). Multiple system atrophy (MSA) is a neurodegenerative disorder characterized by autonomic failure (cardiovascular and/or urinary), parkinsonism, cerebellar impairment and corticospinal signs with a median survival of 6-9 years. "Another research group performed circRNA sequencing of the brain samples from multiple system atrophy (MSA) patients and identified five circRNAs, namely IQCK, MAP4K3, EFCAB11, DTNA, and MCTP1, that were overexpressed in the white matter of the cortical tissue." (PMID 33269108, 2020).
ovarian carcinoma (1 paper, 2021). A malignant neoplasm originating from the surface ovarian epithelium. "Moreover, previous studies have identified that MCTP1 is associated with the drug resistance in ovarian cancer cell lines." (PMID 33571139, 2021). "Notably, the previous studies also indicated that MCTP1 participates in the drug-resistance in ovarian cancer cell lines." (PMID 33571139, 2021).
psychosis (1 paper, 2021). "The mutation or expression of MCTP1 variants is related to neuro psychosis." (PMID 34093644, 2021).
cancer (7 papers, 2017 to 2023). A tumor composed of atypical neoplastic, often pleomorphic cells that invade other tissues. "We also found mutations in SMAD3, a transcription factor belonging to the TGF‐β signaling pathway that plays a key role in many tumors, and in MCTP1 gene, whose mutations have been recently associated with acquired drug resistance in carcinomas." (PMID 35212153, 2022). "Microarray analysis of cancer tissues from AOM/DSS and AOM/DSS/Ab mice revealed profound differences in the expression of genes associated with mast cells, namely Mctp1, Mctp2, Mctp4, Cma1, Fcer1a, Pla2g2e, and Cpa3." (PMID 37185713, 2023). "In this work, we identified that MCTP1 participates in the multi-drug resistance of EC cancer, which has implications for the design of new biomarker for the potential therapeutic treatment of EC." (PMID 33571139, 2021). "Thus, the significance of MCTP1 expression in cancer progression and drug resistance requires further investigation." (PMID 29649113, 2018). "Thus, the role of MCTP1 expression in cancer and cancer drug resistance requires further investigation." (PMID 29027969, 2017). "However, only rare cases are reported showing that MCTP1 are related to the cancer development." (PMID 33571139, 2021).
tumor (3 papers, 2016 to 2022). "Variation in the expression level of the MCTP1 gene in tumor tissues was strongly correlated with patient’s age." (PMID 35845311, 2022). "There was considerable variation between tumor groups when compared to the control group and MCTP1 was upregulated in tumor groups by a mean factor of 2.844 (P ≤.0.010)." (PMID 35845311, 2022). "Also, variation in expression level of the MCTP1 gene in tumor tissues was strongly correlated with patient’s age (P ≤ 0.018)." (PMID 35845311, 2022). "While only the FOXM1, PYROXD1, hTERT and MCTP1 genes were overexpressed in CRC tumor tissues relative to the normal adjacent tissues at all the stages, but FOXM1, PYROXD1, hTERT, PIM3, BMI1, PPARA and MCTP1 were found to have stage-dependent expression." (PMID 35845311, 2022).
MCTP1 also shares sentences with these, for which no sentence is quoted: Brain diseases (1 paper); breast carcinoma (1); depression (1); lung carcinoma (1).